CBS (cystathionine beta-synthase)
Diseases named in the same sentence as CBS in open-access papers (continued):
Sharing a sentence is not in itself a finding about the gene and the disease.
Myocardial fibrosis (1 paper, 2025). "The contribution of the H2S/CBS pathway to high-salt–induced myocardial fibrosis (MF) was explored, with a focus on the mechanistic involvement of hypoxia-inducible factor-1α (HIF-1α)." (PMID 40642013, 2025).
nicotine addiction (1 paper, 2014). "CBS enzyme, which mediates the conversion of homocysteine to cystathionine, can contribute to regulation of epigenetic changes and specifically, SNPs in CBS and MTRR are reported to induce hypermethylation of promoter region in lung epithelial cells of individual's with nicotine addiction." (PMID 25657617, 2014).
non-small cell lung adenocarcinoma (1 paper, 2022). Type of epithelial lung cancer arising from glandular origin. "Studies have shown that in human non-small-cell lung adenocarcinoma, tumor cells express more CBS than adjacent normal lung tissue cells." (PMID 36558139, 2022).
oral cancer (1 paper, 2016). "Therefore, this study aimed to investigate the frequency and association of MTHFR and CBS polymorphisms in oral cancer susceptibility in the population of the state of Espírito Santo, Brazil and its potential impact on the prognostic outcome." (PMID 26749456, 2016).
osteoarthritis (1 paper, 2024). A noninflammatory degenerative joint disease occurring chiefly in older persons, characterized by degeneration of the articular cartilage, hypertrophy of bone at the margins and changes in the synovial membrane. "Rutin is found to negatively regulate RhoA/ROCK signaling by promoting the expression of CBS, effectively inhibiting the inflammatory progression of osteoarthritis." (PMID 37938371, 2024). "Overall, we postulate that curcumin might have therapeutic potential in the management of osteoarthritis by targeting CBS, PSAT1, MAOA, and other crucial proteins." (PMID 37938371, 2024). "For instance, curcumin may exhibit therapeutic effects on osteoarthritis by modulating the CBS, CTH, PSAT1, MAOA, and AOC2 proteins involved in the metabolism of glycine, serine, and threonine." (PMID 37938371, 2024). "Moreover, curcumin may have therapeutic effects on osteoarthritis by interacting with the CTH, CBS, CDO1, and PSAT1 proteins involved in cysteine and methionine metabolism." (PMID 37938371, 2024).
Osteoblastoma (1 paper, 2022). A rare benign bone-forming neoplasm usually arising from the spine. "CBS, CSE, and H2S are highly expressed in human malignant osteoblastoma cells." (PMID 36408214, 2022).
osteosarcoma (1 paper, 2018). A usually aggressive malignant bone-forming mesenchymal neoplasm, predominantly affecting adolescents and young adults. "However, to our knowledge, there was no report about CBS in osteosarcoma, so it might be a novel target for the diagnosis or treatment of osteosarcoma." (PMID 29760609, 2018).
Pain (1 paper, 2015). An unpleasant sensory and emotional experience associated with actual or potential tissue damage, or described in terms of such damage. "The targeting of CBS/H2S signaling may be a potential treatment strategy for chronic radicular neuropathic pain." (PMID 25885215, 2015).
periodontal diseases (1 paper, 2022). "A recent study aiming to compare the periodontium of the CBS+/-mouse model to the wild type suggests a significant correlation between periodontal diseases and CBS deficiency." (PMID 35116090, 2022).
pernicious anemia (1 paper, 2014). Megaloblastic anemia caused by vitamin B-12 deficiency due to impaired absorption. "In this regard, it is interesting that multinucleated cells are seen in the fatty livers of humans with CBS defect, the CBS knock-out mouse, pups from B12-deficient rats, and in the bone-marrows of humans with pernicious anemia." (PMID 24950438, 2014).
prostate tumor (1 paper, 2024). "CBS protein was present in the prostate tumor of 15-week-old TRAMP B6; FVB F1 mice but higher in 19-week-old TRAMP B6; FVB F1 mice, which models aggressive PCa." (PMID 38172561, 2024).
psoriasis (1 paper, 2021). An autoimmune condition characterized by red, well-delineated plaques with silvery scales that are usually on the extensor surfaces and scalp. "Based on the sequencing results, the genes of CBS, Sardh, GNMT, Pgam2, and Sdsl in the Gly-Ser-Thr axis were selected for the determination of protein concentrations on day 12 to explore the involvement of this metabolic pathway in the TDG treatment of psoriasis." (PMID 33995034, 2021).
pulmonary disease (1 paper, 2020). "Our findings suggest that Mtb elicits a deleterious host response via CBS to promote progressive pulmonary disease." (PMID 31992699, 2020).
rectal adenocarcinomas (1 paper, 2023). "In contrast, rectal adenocarcinomas show higher CBS expression compared to non-neoplastic tissue." (PMID 37483514, 2023).
sarcopenia (1 paper, 2022). Progressive decline in muscle mass due to aging which results in decreased functional capacity of muscles. "In conclusion, in an in vitro model of sarcopenia, an impairment in CBS/CSE/H2S signalling occurs, whereas glucoraphanin, a natural H2S-releasing molecule, appears more effective for preventing the SKM damage." (PMID 35682634, 2022). "In conclusion, this study provides molecular insights into the relevance of the CSE/CBS/H2S system in sarcopenia." (PMID 35682634, 2022).
ulcerative colitis (1 paper, 2021). An inflammatory bowel disease involving the mucosal surface of the large intestine and rectum. "In addition, the decreased expression of CBS propagates the pathogenesis of ulcerative colitis by exacerbating inflammation-induced intestinal barrier injury, implying an important role of CBS in mediating organ damage." (PMID 34925701, 2021).
uremia (1 paper, 2018). A clinical syndrome associated with the retention of renal waste products or uremic toxins in the blood. "It is worth noting that CBS and CSE have been previously found to be downregulated in uremia and also that Nrf2 and AKT, involved in the response to oxidative stress, are downregulated in renal disease development." (PMID 29710830, 2018). "This may indicate that the MST increase, in this disease, is not capable of counterbalancing the decrease of CBS and/or CSE expression described both in the patients and in uremia animal models." (PMID 29710830, 2018).
ureteral obstructive (1 paper, 2015). "After unilateral ureteral obstruction, CBS and CSE expressions in ureteral obstructive mice kidneys were gradually downregulated in a time-dependent pattern, consistent with decreased plasma and tissue H2S levels and aggravated interstitial fibrosis in the kidney after UUO." (PMID 26078809, 2015).
Usher syndrome (1 paper, 2025). A syndromic diseae characterized by the association of sensorineural deafness (usually congenital) with retinitis pigmentosa and progressive vision loss. "Among these, WNT5A and CBS were significantly downregulated in Usher syndrome, whereas the remaining eight genes showed upregulation." (PMID 40723835, 2025). "Several genes, such as IGHV1-69D, CTSH, and LMO7, exhibited significant upregulation in Usher syndrome, while others, including SLC3A2, ABLIM1, and CBS, were notably downregulated." (PMID 40723835, 2025).
vitamin B group deficiency (1 paper, 2025). "However, several conditions such as genetic mutations of CBS or polymorphism of MTHFR, vitamin B group deficiency, aging, and certain medication can increase the homocysteine levels of the blood plasma." (PMID 40149955, 2025).
vitiligo (1 paper, 2022). Generalized well circumscribed patches of leukoderma that are generally distributed over symmetric body locations and is due to autoimmune destruction of melanocytes. "MTHFR and CBS are the major determinants of homocysteine metabolism and studies have shown significantly higher level of homocysteine in vitiligo patients." (PMID 36008553, 2022).
cancer (107 papers, 2012 to 2026). A tumor composed of atypical neoplastic, often pleomorphic cells that invade other tissues. "Different studies found that higher levels of H2S in multiple cancer types and inhibition of H2S production via suppression of CBS or CSE activities cause a reduction in tumor growth in multiple cancer types." (PMID 37627515, 2023). "The low expression level of CBS is associated with poor survival in cancers with CBS as a tumor suppressor." (PMID 36733406, 2023). "It is predicted that high CBS expression is associated with a poor survival rate for patients with high-CBS-expressing cancers." (PMID 37283791, 2023). "In fact, CBS has been reported to be aberrantly expressed, accompanied by increased H2S levels in lung cancer and other types of cancer, being associated with carcinogenesis support and chemoresistance." (PMID 38247476, 2023). "This mutation is the most frequently observed CBS mutation in cancer cells and exhibits only ~2.4% of the enzyme activity of wild type CBS." (PMID 35758651, 2022). "Depending on the type of cancer, CBS, CSE and/or 3-MST have been implicated as enzymatic sources of H2S." (PMID 32183148, 2020). "With the identification of the pathogenic role of CBS in cancer, the use of CBS as a prognostic and predictive biomarker is becoming attractive." (PMID 30050925, 2018). "Loss of CBS severely compromises cell viability that is exacerbated upon cisplatin treatment in cancer cells." (PMID 24236104, 2013). "Thus, although the underlying mechanisms are markedly different, CBS inhibition emerges in both cancer and DS as a potential experimental therapeutic intervention." (PMID 35864237, 2022). "Further studies on the cross talk between CBS and ferroptotic process in cells is necessary to elucidate the explicit role and underlying molecular mechanisms of transsulfuration pathway in the death of cancer cells." (PMID 30258181, 2018). "Indeed, a growing number of human pathologies, from cardiovascular and neurodegenerative diseases to different cancer types, are reportedly associated with disturbances of H2S metabolism related to CBS, CSE, and/or MST." (PMID 28421128, 2017). "However we demonstrate that GSH and H2S and not Hcy are the primary causal factors for oxidative stress observed in CBS silenced cancer cells." (PMID 24236104, 2013). "These ISR-activated cancer cells exhibited broad chemoresistance and apoptosis resistance, yet were auxotrophic for serine due to loss of PHGDH and CBS expression, impairing serine and cysteine biosynthesis." (PMID 41704035, 2026). "In summary, it is documented that several types of cancer cells overexpress CBS, CSE or 3MST or synthesize larger amounts of H2S compared to adjacent non-tumor tissue." (PMID 41373571, 2025). "In fact, in a cancer cell model, forced CBS expression was previously found to induce a metabolic shift toward the pentose-phosphate pathway." (PMID 40187942, 2025). "The effectiveness of benserazide as a CBS inhibitor in cancer treatment requires further validation through extensive preclinical and clinical studies." (PMID 40442106, 2025). "(It should be noted that a similar metabolic rearrangement also occurs in cancer cells in response to CBS upregulation)." (PMID 40187942, 2025). "CBS is involved not only in cancer cells but also in crucial physiological processes such as sulfur metabolism and antioxidant responses." (PMID 40442106, 2025). "Our observations also revealed that benserazide had an inhibitory effect on the expression of CBS protein in cancer cells." (PMID 38828455, 2024). "In recent years, our research investigations have focused on the presence and role of enzymes (MPST, CTH, CBS) involved in the metabolism of low-molecular-weight sulfur compounds and H2S in normal and/or cancer cells." (PMID 38397425, 2024). "In recent years, there has been growing interest in the role of CBS and H2S in cancer development and progression." (PMID 38828455, 2024).
cancer (continued). "CBS produces H2S at low to moderate levels in the early stage of cancer development, which acts as a bioenergetic factor for cancer cell growth and promotes vasorelaxation generation, supporting tumor growth and proliferation." (PMID 38448410, 2024). "Further understanding the metabolic roles of CBS and its metabolites, homocysteine, and H2S, is crucial for unraveling cancer biology, offering insights into cancer pathogenesis, and enhancing therapeutic strategies." (PMID 39062461, 2024). "Previous research has indicated that Cystathionine β-synthase (CBS) is highly expressed and contributes to the progression of various types of cancer." (PMID 38828455, 2024). "The newer generation of drugs selectively targeting key metabolic enzymes in SGOC metabolism, such as PHGDH, MTHFDs, DHFR, TYMS, GART and CBS, will provide a new strategy for cancer treatment in the future." (PMID 37147729, 2023). "Taken together, it appears that in EO771 cells, H2S generation from 3-MST plays a more prominent cancer-cell-supporting role, and the functional role of CBS and/or CSE is relatively minor." (PMID 36978895, 2023). "The enzymatic source of H2S was found to be CBS in many cancer types; but in some models, CSE and/or 3-MST were found to contribute as well." (PMID 36978895, 2023). "The high proliferation of cancer cells creates redox stress conditions inside the cells, which activates the CBS gene to produce H2S through the 272CXXC275 motif." (PMID 37627515, 2023). "Elevated enzymes of H2S have been observed in many types of cancers, and tumor growth in cancers such as colon and lung cancer has been inhibited due to a decrease in CBS or CTH activity." (PMID 37895865, 2023). "Since the cytoskeleton is crucially involved in carcinogenesis and is a target of some groups of chemotherapeutics, cancer cell growth and proliferation due to the potential interaction with CBS was studied as well." (PMID 37483514, 2023). "There are three principal enzymatic sources of H2S in various cancer cells: cystathionine β-synthase (CBS), cystathionine γ-lyase (CSE) and 3-mercaptopyruvate sulfurtransferase (3-MST)." (PMID 36978895, 2023). "Expression of CBS differs in individual types of cancer and is definitely dependent on the cancer grade." (PMID 37483514, 2023). "Recent studies revealed that cancer cells increased the expression of CBS (the rate-limiting enzyme in transsulfuration reaction) to reduce excess Hcy levels and produce H2S." (PMID 37627515, 2023). "Consistent with this, depletion of H2S production via knockdown of CBS was also found to reduce ATP production in cancer cells." (PMID 37627515, 2023). "Inhibition of CBS exerts suppression of cancer cell functions, while in DS, it results in normalization of H2S biogenesis and mitochondrial function." (PMID 35864237, 2022). "Bhattacharyya and colleagues demonstrated that CBS inhibition sensitizes cancer cells to chemotherapy, both in vitro and in vivo." (PMID 35684331, 2022). "CBS knockdown of cancer cells inhibited xenograft development and neovessel density, indicating a function for endogenous H2S in tumor angiogenesis." (PMID 35684331, 2022). "CBS plays a complex role in cancer pathogenesis having purported tumor-promoting and -suppressive roles." (PMID 35758651, 2022). "Aberrant CBS expression and/or activity contributes to a wide range of diseases including hyperhomocysteinemia and cancer." (PMID 35758651, 2022). "The downregulation of CBS via small molecule inhibitors or siRNAs reduced antioxidant capacity and therefore enhanced the sensitivity of cancer cells to chemotherapy." (PMID 35084545, 2022). "The role of CBS in cancer development has been well-reviewed elsewhere, and we will here focus on those studies that regard both Se and CBS." (PMID 36358931, 2022).
cancer (continued). "In 2013, the concept that cancer cells overexpress the transsulfuration enzyme cystathionine β-synthase (CBS) and use its enzymatic product, hydrogen sulfide (H2S), was formulated, first in colon cancer and subsequently in ovarian cancer." (PMID 36139896, 2022). "The results show that the expression of CBS in cancer cell lines is significantly higher than that in the untransformed lung epithelial cell line Beas2B control." (PMID 36558139, 2022). "Based on our observation that loss of CBS promoted AIS escape in normal cells, we propose a potential tumor-suppressive role for CBS in cancers harboring PI3K/AKT pathway activation." (PMID 35758651, 2022). "As with CGL, most cancer studies have focused on the role of CBS in the production of H2S and how H2S supports tumor growth." (PMID 36358931, 2022). "More recently, we have demonstrated that resistance to the chemotherapeutic agent 5-fluorouracil was associated with increased CBS protein levels and that inhibition of CBS activity restored cancer cell chemosensitivity." (PMID 34439739, 2021). "Using RNA-seq, we determined the global changes of mRNAs and miRNAs and found the downregulation of miR-559, a potential tumor-suppressive miRNA, and upregulation of CBS, a cancer-related gene, after DiAcSpm treatment." (PMID 34603448, 2021). "The relevance of the trans-sulphuration pathway in the survival of cancer cells and reversion of ferroptosis was also proven by silencing CBS, thus inhibiting cysteine synthesis." (PMID 33223534, 2021). "The role of H2S in cancer was demonstrated in 2013 when increased cytoplasmic and mitochondrial CBS expression was detected in seven colorectal carcinoma resections, compared to benign adjacent colonic tissues." (PMID 35366284, 2021). "Further downregulation of the CBS enzyme using an inhibitor CH004 induces anti-cancer effects via ferroptosis, an iron-dependent programmed cell death in HepG2 cells." (PMID 33390834, 2021). "The novel studies of CBS in different types of cancer models suggest CBS is a promising anti-tumor therapeutic target." (PMID 34439295, 2021). "The ratio of CBS to H2S plays a vital role in cancer progression, including in ovarian cancer and breast cancer." (PMID 34062820, 2021). "In colon cancer, the increased expression and activity of CBS and CSE is associated with high rates of proliferation and migration of cancer cells, controlled, respectively, by PI3K/AKT and Wnt pathways." (PMID 32714858, 2020). "Not only mitochondrial function is regulated in cancer cells in a CBS-dependent fashion, but also mitochondrial morphology." (PMID 32365821, 2020). "In these studies, multiple tumor tissues from patients and cancer cell lines have been tested for CBS expression, and revealed increasing mRNA and/or protein levels compared to adjacent normal tissue or non-malignant equivalent cells." (PMID 32365821, 2020). "Somatic mutations in CTCF binding sites of the CTCF-cohesin complex (CBS) are widely observed in cancer genomes." (PMID 32012149, 2020). "It is interesting to note that most of the cancer types for which a putative antineoplastic action of disulfiram has been reported are also forms of tumor where CBS has been shown to be overexpressed." (PMID 32365821, 2020). "In thyroid cancer, CBS is the major responsible for H2S production, which activates cancer cells proliferation and migration, through ROS/PI3K/AKT/mTOR and MAPK pathways." (PMID 32714858, 2020). "Using CBS silencing, several studies have investigated the functional role of CBS in various cancer cells." (PMID 32365821, 2020). "The mechanism by which CBS supports cellular bioenergetics in cancer cells is related, at least in part, to a direct donation of electrons to the mitochondrial electron transfer chain." (PMID 32365821, 2020). "As discussed in the subsequent chapter, CBS overexpression and H2S overproduction is now viewed as an important factor in the bioenergetic activation and metabolic reprogramming of cancer cells." (PMID 32365821, 2020).